SDC1 (syndecan 1)
Diseases named in the same sentence as SDC1 in open-access papers (continued):
Sharing a sentence is not in itself a finding about the gene and the disease.
cancer (continued). "Syndecan-1 has been reported to have prognostic value in many types of cancers such as hepatocellular cancer, laryngeal cancer, gastric cancer, and lung cancer." (PMID 26518017, 2015). "Collectively, SDC1 represents an attractive molecular target for further evaluation in personalized cancer treatment." (PMID 26293675, 2015). "Normal oral mucosa has been shown to express moderate-to-high levels of SDC1, which is reduced or abolished in carcinomas." (PMID 26293675, 2015). "It is also likely that SDC-1 shedding upregulates the SDC-2 synthesis affecting positively the proliferation of the cancer cells." (PMID 24551591, 2014). "The ratio of membrane-bound and shed syndecan-1 is altered in certain pathological conditions, including cancer and metastasis." (PMID 25147801, 2014). "In the malignant cell, syndecan-1 participates in the regulation of basic functions such as proliferation and cell migration, thereby possibly influencing the cancer progression and ultimately patient survival." (PMID 25147801, 2014). "SDC-1 is expressed mainly in epithelial tissues, hence, studies aiming to address its role in malignancies have focused on carcinoma." (PMID 24524203, 2014). "The release of soluble syndecan-1 from cell membrane by proteolytic degradation marks a switch from a proliferative to an invasive phenotype in cancer cells." (PMID 23844358, 2013). "At a molecular level, FGF2 binds to multiple membrane bound receptors in human cancers, including SDC1, and this receptor binding can trigger multiple signaling pathways, including those involved in cell proliferation and survival." (PMID 23988031, 2013). "As Syndecan-1 modulates the cancer stem cell phenotype via regulation of the Wnt and IL-6/STAT3 signaling pathways, it emerges as a promising novel target for therapeutic approaches." (PMID 24392029, 2013). "Experimental studies have shown that membrane-bound and soluble forms of syndecan-1 have opposing effects on cancer cell functions." (PMID 24392351, 2013). "Side population measurement by Hoechst dye exclusion and Aldehyde dehydrogenase-1 activity revealed that Syndecan-1 knockdown in MDA-MB-231 cells significantly reduced putative cancer stem cell pools by 60% and 27%, respectively, compared to controls." (PMID 24392029, 2013). "Similar to carcinoma cells, however, the effects are cell-type dependent and seem to be governed by the spatio-temporal expression of syndecan-1." (PMID 24392351, 2013). "Most studies dealing with the effect of syndecans on signaling, have been performed in carcinomas or hematological malignancies; thus the function of syndecan-1 is less studied in mesenchymal cells." (PMID 24392351, 2013). "This broader systemic approach indicates that syndecan-1 plays a central role in most functions considered hallmarks of cancer, including adhesion, migration, proliferation, invasion, cell cycle regulation, cell death and angiogenesis." (PMID 23144729, 2012). "Silencing of syndecan-1 highly altered several cell-cycle related pathways along with several cancer-related functional gene sets." (PMID 23144729, 2012). "Syndecan-1 is expressed principally in epithelial tissues; hence studies aiming to address its role in malignancies examine mostly carcinomas." (PMID 22745764, 2012). "We have recently shown that MT1-MMP cleaves syndecan-1, a proteoglycan induced in stromal fibroblasts by neighboring carcinoma cells in vivo and in vitro." (PMID 23056402, 2012). "Based on previously investigations, it is possible that the soluble syndecan-1 also has an effect on carcinoma cells and it will be investigated in future studies." (PMID 22905270, 2012). "Syndecan-1 can be redistributed from the epithelial cells to the stroma compartment in postmenopausal cancers." (PMID 20398359, 2010). "A recent study using A549 cells, a carcinoma-derived alveolar type II cell line, reported that knockdown of syndecan-1 expression slowed cell migration." (PMID 19668337, 2009).
cancer (continued). "This review summarizes studies relating PUFAs to PPARγ and cancer and offers a new paradigm relating an n-3 PUFA through PPARγ to the expression of the cell surface proteoglycan, syndecan-1, and to the death of cancer cells." (PMID 18769551, 2008). "Recent studies haveidentified the heparan sulfate proteoglycan, syndecan 1, as a target for PPARγ in human breast and prostate cancer cells." (PMID 18769551, 2008). "Carcinoma cells lack syndecan-1 expression when they are transiting from an epithelial to a less-differentiated mesenchymal phenotype (epithelial–mesenchymal transition, EMT)." (PMID 18542065, 2008). "These complex data point to a need for continuing assessment of syndecan-1 status in relation to the clinico-pathological characteristics of carcinomas from different tissue sources." (PMID 18590537, 2008). "Of major interest, a shift of syndecan-1 expression from malignant epithelial cells to reactive stromal cells has also been observed in many carcinomas during their progression." (PMID 18542065, 2008). "SDC1 displayed a spotted cytoplasmic staining pattern in cancer cells often with an accentuation close to the nucleus." (PMID 16265353, 2005). "We observed an increase in cytoplasmic SDC1 staining in cancer cells (100%) compared to normal urothelial cells (65%)." (PMID 16265353, 2005). "Additionally, analysis of the TCGA dataset showed a strong correlation between SDC1 expression and cancer stem markers." (PMID 41364407, 2025). "Given the interplay between sortilin and syndecan-1, therapeutic approaches that can target both molecules could address the dual phases of cancer development/progression and help prevent metabolic shifts in either direction." (PMID 41303628, 2025). "Our study revealed that SDC1 plays diverse roles in pan-cancer, which may be correlated with immune cell infiltration and cell stemness based on the TCGA dataset." (PMID 41364407, 2025). "In this study, we investigated SDC1 expression, OS and mechanism in pan-cancer." (PMID 41364407, 2025). "The role of SDC1 is altered during tumorigenesis in different cancer types." (PMID 40542654, 2025). "Furthermore, we previously demonstrated that SCGB3A2 (also called UGRP1 (uteroglobin-related protein 1)), another member belonging to the same SCGB3A gene subfamily as SCGB3A1, is a ligand for Syndecan-1 (SDC1) in cancer cells." (PMID 41469838, 2025). "In addition to its critical role in maintaining homeostasis, SDC1 is involved in the development and progression of various pathological conditions, including cancer." (PMID 40542654, 2025). "It has also been proposed that targeting SDC1 could provide new opportunities in cancer therapy, and several agents targeting SDC1 have been developed and some of them are already in phase I or II trials in cancer." (PMID 39777501, 2025). "The combination of sortilin and syndecan-1 can be used to accurately map and interpret the grade of the cancer, giving a complete picture of the cancer biology and identifying early-stage through to late-stage cancer." (PMID 41303628, 2025). "Notably, the majority of MP and AIP lesions (83%) had comparable or higher expression of Syndecan-1 than that expressed in the cancer component, versus levels observed in flat or tufting HGPIN lesions (20%)." (PMID 37704825, 2024). "For non-cancer studies, the miDRB-targeted exosome biogenesis genes for ferroptosis-inhibiting miRNAs are retrieved as follows: miR-19a-3p (SDC1, VPS4B, and MYO5B), miR-424-5p (VPS4A and MYO5B), miR-4291 (ATP9A, SMPD3, TSG101, and MYO5B), miR-522-3p (PDCD6IP), and miR-670-3p (CD34 and RAB27A)." (PMID 38892270, 2024). "SDC-1 is overexpressed in cancers and is shed into the extracellular environment." (PMID 38396744, 2024). "Several studies have documented syndecan-1 (SDC1) expression changes across various carcinomas." (PMID 39728992, 2024).
cancer (continued). "Moreover, we focused our study on brain metastases (17/23 cases) based on our previous findings documenting surface syndecan-1 overexpression on CSF floating cancer cells of BC patients with central nervous system involvement." (PMID 36088392, 2023). "Dysregulated expression of SDC1 in cancer has prognostic relevance and clinical significance." (PMID 37056938, 2023). "We also found that the interaction of PTN- SDC1 and PTN- NCL may mediate the effect of B cells and CD8 + T cells on cancer-associated fibroblast-related HCC." (PMID 37259127, 2023). "A canonical signaling about syndecans in cancer is heparinase/syndecan-1 pathway." (PMID 36906534, 2023). "Syndecan-1 has a direct link to key proteins involved in lipid metabolism and also binds to a range of other extracellular and membrane proteins, including αVβ3 integrin, that promote cancer progression." (PMID 37596305, 2023). "In addition, HSPGs such as syndecan-1 can promote the assembly of parallel fibronectin and collagen-1 fibers facilitating the directional migration of cancer cells." (PMID 36693448, 2023). "Furthermore, SDC1 and E-cadherin seem to be coordinately expressed in several cancer types, therefore affecting cancer EMT and progression." (PMID 36980680, 2023). "However, as CD138 (syndecan-1) is highly expressed in some solid tumors and hematological malignancies, studies found new opportunities in treating cancers by targeting syndecan-1." (PMID 37542221, 2023). "The disorder of SDC1 expression was also significantly correlated to poor prognosis of cancers." (PMID 35342420, 2022). "SDC1 exemplifies the impact that proteoglycans can have on the architecture of the cancer stromal microenvironment, which in turn influences the behavior of cancer cells." (PMID 35454809, 2022). "Studies show that the expression of SDC1 is different in different cancer types." (PMID 35669186, 2022). "In experimental hepatocarcinogenesis, syndecan-1 overexpression provides protection against the development of cancer, and in addition to other factors, the downregulation of SPOCK1 could be observed throughout the experimental period." (PMID 35186754, 2022). "Although the role of SDC1 in BC remains unclear, its crucial function in other human cancer has been studied in detail." (PMID 36388159, 2022). "Moreover, high Sdc-1 expression correlated with a poor prognosis in Kaplan-Meier survival analysis, suggesting the important role of Sdc-1 in the progression of this type of cancer." (PMID 35155241, 2022). "Glypican proteoglycan (GPC1 and GPC6), core membrane-anchored heparan sulfate proteoglycans, were upregulated in ESCC tissues compared with para-carcinoma tissues, whereas syndecan proteoglycans (SDC1, SDC2, and SDC4), transmembrane heparan sulfate proteoglycans, were downregulated." (PMID 35840985, 2022). "Previous studies have demonstrated that SDC1 has different effects in different cancers." (PMID 35087751, 2021). "Space precludes a comprehensive analysis of all mouse cancer models and involvement of syndecan-1." (PMID 33921767, 2021). "Levels of both membrane-bound as well as shed SDC-1 are often altered in malignancies." (PMID 33562126, 2021). "Interestingly, some studies on the stroma of various cancers have shown a different role for syndecan-1 in the stroma compared to the epithelium." (PMID 31540870, 2021). "One of the possible mechanisms for SDC-1 involvement in cancer is the shedding process." (PMID 33562126, 2021). "Importantly, SDC-1 is a potentially attractive molecular target that can guide individualized cancer diagnosis and treatment." (PMID 35118073, 2021). "Specific alterations in miRNA expression have been speculated to affect SDC-1 signaling and promote cancer progression." (PMID 35118073, 2021). "Dysregulation of SDC-1 may promotes carcinogenesis, cancer recurrence and resistance to chemotherapy." (PMID 35118073, 2021).
cancer (continued). "A survey of the many studies on syndecan-1 and carcinomas shows that mis-localization of the proteoglycan may be a key feature." (PMID 33921767, 2021). "Many reports have shown that syndecan-1 levels are altered in carcinomas of several types." (PMID 33921767, 2021). "Notably, normal tissues of the gastro-intestinal tract have high levels of Sdc-1, which suggests that Sdc-1 expression is lost at some point during cancer development and progression in some of the patients, conferring a survival advantage." (PMID 33330449, 2020). "Syndecan-1 on the surface of cancer cells appears to be a positive prognostic marker." (PMID 32388727, 2020). "Syndecan-1 is targeted by miR-10b which promotes cancer cell motility and invasiveness." (PMID 33321819, 2020). "Sdc-1 is found in several normal tissues, as well as in the malignant tumors." (PMID 33330449, 2020). "This might be of high impact during bone regeneration or bone diseases like cancer where Syndecan-1 expression is known to be even more prevalent." (PMID 33239699, 2020). "Using anti-estrogens as well as HSPE inhibitors developed for cancer treatment and in use in clinical trials, and the SDC1 specific inhibitor SSTN, we investigated their effects in patient-derived explants of normal mammary tissue cultured over a 2 week period." (PMID 32760722, 2020). "SDC1 is expressed by normal epithelial and endothelial cells and by carcinoma cells as well." (PMID 33114033, 2020). "Interestingly, we have found that Sdc-1 mRNA expression in carcinoma tissue of IBC patients negatively correlated with expression of IL-17, whereas positively correlated in the carcinoma tissue of non-IBC patients." (PMID 31145753, 2019). "Moreover, blocking the pro-tumorigenic activity of syndecan-1 by its specific antibody, i.e., Nbt062 and B-B4 mAb, is another good option in treating several cancers." (PMID 30135409, 2018). "Moreover, measurement of shedded syndecan-1 serum levels by ELISA in prostate patients revealed a correlation of higher levels with advanced cancer stage as well as with adverse overall survival and DSS in a multivariable pre-operative model." (PMID 29559954, 2018). "Syndecan-1 is a cell surface heparin sulfate proteoglycan, which is expressed by many cancers." (PMID 29796177, 2018). "Interestingly, shedding of syndecan-1 was reported to be positively correlated with cancer development in mice." (PMID 30135409, 2018). "As expected, Sdc1 was also expressed by carcinoma cells in mouse and human samples." (PMID 29976229, 2018). "Sdc1 was expressed in the epithelium of 90% carcinoma of both histological types." (PMID 30151336, 2018). "Syndecan-1 regulates the adhesion of cancer cells to lymphatic vessel endothelium." (PMID 27928742, 2017). "SDC1 has been identified in human cancers, including hematological malignancies and solid tumors." (PMID 29340066, 2017). "In addition, we examined SDC1 expression in cancer cells using immunohistochemistry and found that SDC1 expression was reduced in the SDC1 knockdown group compared to the control/scramble group." (PMID 28422726, 2017). "Together, SDC1 may not only act as a potential therapeutic target, but also as a novel prognostic biomarker in cancer." (PMID 29340066, 2017). "Nuclear localization of syndecan-1 has been reported, suggesting that it may function as a transcription factor and therefore impact gene regulation affecting cancer pathogenesis." (PMID 26869927, 2016). "Alterations in the levels of soluble SDC1 have been reported in various cancer types." (PMID 26293675, 2015). "It has been reported that bFGF/FGF2 induces shedding of SDC1 in cancer cells." (PMID 26293675, 2015). "The SDC1 expression profile varies among cancer types, but the differential expression signatures between normal and cancer cells in epithelial and stromal compartments are directly associated with aggressiveness of tumors and patient's clinical outcome and survival." (PMID 26293675, 2015).
cancer (continued). "A significant reduction of both syndecan-1 and E-cadherin expression was also seen in severely dysplastic epithelium as compared to moderate dysplasia in colorectal-adenoma, with further reduction of both molecules in carcinomas compared to adenomas." (PMID 26420915, 2015). "In addition, immunohistochemical (IHC) staining assessed SDC-1 protein expression in 193 bladder specimens (185 cancer subjects and 8 non-cancer subjects)." (PMID 24524203, 2014). "This suggests a more general pathophysiological role of syndecan-1 in cancers." (PMID 25147801, 2014). "Generally, SDC1 expression is reduced in most malignant tumors." (PMID 24373193, 2013). "Clinical significance of SDC1 expression has been tested in several cancers." (PMID 24373193, 2013). "The expression of syndecan-1 and its role as a stimulatory or inhibitory factor probably depends upon the concentration of various mitogens, enzymes, and signaling molecules that are specific for each cancer type and histologic grade." (PMID 24392351, 2013). "In addition, the role of syndecan-1 in regulating inflammation in a variety of disease models including cancer has been previously reported." (PMID 22396913, 2012). "The expression of syndecan-1 appears generally down-regulated in human carcinomas and in experimental cancer models, whereas transfectional expression of syndecan-1 in cultured cancer cells has been shown to inhibit their growth and other aspects of malignant behavior." (PMID 22396913, 2012). "Syndecan-1 modulates the biological behaviour of parenchymal cells in several types of carcinomas." (PMID 22745764, 2012). "In summary, studies to date indicate a complicated relationship between SDC-1 and cancer." (PMID 21655218, 2011). "A number of studies have investigated the expression of SDC-1 in human carcinomas." (PMID 19865524, 2009). "Furthermore, a shift of syndecan-1 expression from malignant epithelial cells to reactive stromal cells has also been observed during progression of many carcinomas." (PMID 18542065, 2008). "Finally, various heparan sulfate proteoglycans such as syndecan-1 and glypican are known to be expressed by stromal cells in cancer and to modulate the mitogenic effects of multiple heparin-binding growth factors." (PMID 16176582, 2005). "However, the effect of SDC1 expression on different cancers is controversial." (PMID 41364407, 2025). "Similarly, COL4A1 interactions with SDC1 (CD138) on malignant plasma cells may facilitate cancer cell adhesion and survival." (PMID 39596117, 2024). "Further, another study investigating the clinical implications of circulating Syndecan-1 in PCa patients found high levels (>123 ng/mL) of soluble Syndecan-1 in the serum of more advanced PCa patients, which was correlated with worse overall and cancer-specific survival." (PMID 37371647, 2023). "In addition, heparanase is involved in regulating SDC1 loading in exosomes, evident by the high content of SDC1 in exosomes secreted by heparanase-high expressing cells vs. heparanase-low expressing cells, with subsequent impacts on endothelial cells and cancer progression." (PMID 36980680, 2023). "Therefore, the interference with the biogenesis and action of exosomes (possibly via dual heparanase and SDC1 targeting ) could have an excellent impact at multiple levels of cancer hallmarks." (PMID 36980680, 2023). "Additionally, syndecan-1 is essential for new blood vessel maturation in cancer." (PMID 36906534, 2023). "Moreover, Syndecan-1 regulates the adhesion of cancer cells to lymphatic vessel endothelium." (PMID 32961706, 2020). "Moreover, heparan sulfate proteoglycans function as internalizing receptors of cancer cell-derived EVs, and their modification through antitumor action inhibits MM cell growth and angiogenesis via disruption of the heparanase/syndecan-1 (CD138) axis." (PMID 29534557, 2018).